RNU6-409P (RNA, U6 small nuclear 409, pseudogene)
Gene: Small nuclear RNA gene on chromosome 22 (50,691,260 to 50,691,363, reverse strand). Ensembl gene ENSG00000206841.
Homologues: Orthologues: chimpanzee U6 (100% identical), macaque U6 (91% identical). Paralogues in human: RNU6-1145P (90% identical), RNU6-38P (90% identical), RNU6-46P (90% identical), RNU6-664P (90% identical), RNU6-698P (90% identical), RNU6-1042P (89% identical), RNU6-1089P (89% identical), RNU6-1175P (89% identical), RNU6-11P (89% identical), RNU6-1316P (89% identical), RNU6-37P (89% identical), RNU6-86P (89% identical), and 1288 more.